RNU6-205P (RNA, U6 small nuclear 205, pseudogene)
Gene: Small nuclear RNA gene on chromosome 4 (110,278,185 to 110,278,291, forward strand). Ensembl gene ENSG00000212160.
Homologues: Orthologues: chimpanzee U6 (99% identical), macaque U6 (95% identical), pig U6 (79% identical), guinea pig U6 (76% identical), dog U6 (69% identical), guinea pig U6 (67% identical). Paralogues in human: RNU6-15P (81% identical), RNU6-21P (81% identical), RNU6-33P (80% identical), RNU6-345P (80% identical), RNU6-455P (80% identical), RNU6-657P (80% identical), RNU6-723P (80% identical), RNU6-1 (79% identical), RNU6-1060P (79% identical), RNU6-1103P (79% identical), RNU6-116P (79% identical), RNU6-2 (79% identical), and 1285 more.